MMP2 (matrix metallopeptidase 2)
Diseases named in the same sentence as MMP2 in open-access papers (continued):
Sharing a sentence is not in itself a finding about the gene and the disease.
cancer (continued). "The matrix metalloproteinases (MMPs), such as MMP-9 and MMP-2, play a critical role in cancer cell invasion and metastasis, which can degrade most components of the ECM." (PMID 28534824, 2017). "The mRNA levels of cancer-related genes including β-catenin, E-cadherin, Mmp2 and Mmp9 were higher in CK8+/− mice than in WT mice." (PMID 29228570, 2017). "Based on the molecular complexity of the JNK signalling pathways involved in cancer metastasis and development, several metastasis-associated targets were detected in the present study, including the EMT markers, MMP2/9 and Paxillin/FAK." (PMID 29088796, 2017). "Overexpression of MMP2 has been found to be involved in the tumorigenesis, progression and prognosis of some cancers." (PMID 27494889, 2017). "GRP78 promoted cancer metastasis via up-regulation of MMP-2 and MMP-9, the induction of epithelial-mesenchymal transition or activation of NRF-2/HO-1 pathway." (PMID 29069845, 2017). "Hydration of the extracellular matrix (ECM) is an important process that allows cancer cell invasion and metastasis through the secretion of enzymes such as MMP‐2 and MMP‐9." (PMID 28846829, 2017). "Among these MMPs, MMP‐2 plays a crucial role in cancer metastasis by the degradation of type IV collagen, the major component of the cartilage." (PMID 28672103, 2017). "This proinflammatory cytokine was shown to be of importance in the up-regulation of cancer cell-derived MMP2, which in turn mediates invasiveness of brain metastatic melanoma cells in vitro." (PMID 29312881, 2017). "Matrix metalloproteinases (MMPs) play an important role in cancer cell metastasis, as particularly observed for the roles MMP-2 and MMP-9 in the degradation of ECM." (PMID 28424406, 2017). "Studies have reported that the activation of ERK, a key molecule located in the MAPK pathway, is responsible for the activation of MMP-2 and the invasion of cancer cells including GBM cells." (PMID 29285298, 2017). "In current study, we report that CRABP-II enhances cancer cell migration and invasion through regulating IL-8/MMP-2/MMP-14 pathway." (PMID 28881741, 2017). "Some of these markers such as Vimentin and MMP2&9 are accurate indicators for the invasive nature of the found cancer cells." (PMID 29259164, 2017). "In different cancer cell types, PI3K/AKT has been proved to be related with cancer metastasis through regulating activities of MMP-2 and -9." (PMID 28350337, 2017). "In cancer cells, MMP-2 is localized in the invadosomes where it contributes to the degradation of the extracellular matrix, thereby assisting in the invasion process." (PMID 28061441, 2017). "MMP-2-mediated degradation of the stromal proteins promotes invasiveness and tumourigenicity of cancer cells, as was shown by assessment of cancer cell migration or formation of xenograft tumours in an immunodeficient mouse host." (PMID 28382480, 2017). "Most importantly, DBL inhibited transcriptional factor NFκB, which mediates many cancer metastatic characteristics, such as MMP-2 and -9 activities." (PMID 28350337, 2017). "Meanwhile, the abnormal expression of MMP-9, MMP-2, vimentin and CD44v6 in cancer cells would lead to decreased adhesion, enhanced migration and invasion." (PMID 28774312, 2017). "For the three non-cancer diseases related genes (MMP2, VEGFA and CASP8), the percentage is just around 30%." (PMID 28340554, 2017). "The fact that low-risk cancers showed lower Ktrans and Kep values was consistent with their less MVD and lower VEGF-1, MMP-2, and MMP-9 expression levels." (PMID 29371992, 2017). "By regulating the expression of effector molecules including SREBP-1c, VEGF, MMP2, Sp1 plays pivotal roles in cancer cell metabolism, proliferation, and metastasis." (PMID 29262634, 2017). "Based on protein expression of MMP-2/-9 being regulated via complex molecular signaling pathways, next we investigated other mechanisms that also affect MMP-2/-9 or expression of other proteins related with the steps of cancer metastasis." (PMID 28350337, 2017).
cancer (continued). "Previous studies have documented that integrin α5β1 confers invasiveness to cancer cells by regulating the MMP-2 activity and integrin β1 signaling is capable of suppressing RhoA activity and activating MMP-2-dependent cell migration." (PMID 28977889, 2017). "Blocking this paracrine interaction either by pharmacological inhibition of IL-23 or by knocking down cancer cell MMP2 resulted in inhibition of melanoma invasion in vitro." (PMID 29312881, 2017). "IIF also induced differentiation in several cancer cell lines, inhibited MMP-2 and MMP-9 and increased expression of their inhibitors (TIMP-1 and TIMP-2)." (PMID 28465354, 2017). "Western blotting of B16shR-SOCS1 total cell lysate showed decreased expression of MMP2, MMP9 and CD10, implicated in malignant tumor progression, as compared with B16F10-Nex2 total cell lysate." (PMID 28079159, 2017). "During the invasion of cancer cells, the surface of the chip was stained by the Anti-MMP2 epifluorescent markers." (PMID 29259164, 2017). "Several studies have reported that metformin inhibits adhesion and invasion in vitro in a variety of different cancers through multiple cell singling pathways, such as NF-kB, MMP-2/9, AKT/ERK1/2, PKC and JUK/AP-1." (PMID 29340030, 2017). "Collectively, our results strongly suggest a link between FAK, MMP-2, and TnT, and unveil new vulnerabilities that can be exploited to efficiently eradicate cancer cells." (PMID 28423494, 2017). "Inhibition of the protein expressions and enzyme activities of MMP-2/-9 and urokinase is considered to represent a potential therapeutic strategy to suppress cancer metastasis." (PMID 28767067, 2017). "Previous studies have shown that MMPs play an important role in cancer cell metastasis, with significant expression of MMP-2 and MMP-9 in A549 cells." (PMID 28424406, 2017). "With regard to MMP2, all cancer cell lines except ACT-1 cells showed equivalent expression levels to that in Nthy-ori 3-1 cells." (PMID 29137300, 2017). "Our study supports further investigation to determine the role of TnTs in cancer metastasis, cancer cell survival, and of FAK/MMP-2 axis as a therapeutic target for disruption of communication of cancer cells via TnTs." (PMID 28423494, 2017). "The enzyme activities of MMP2 and 3 in GA cancer tissues were higher than those in normal tissues, and MMP8 enzyme activity was lower than those in normal tissues (MMP2, p=0.028; MMP3, p=0.012; MMP8, p=0.0029." (PMID 29285307, 2017). "The top three non-cancer disease genes regulated by the co-functional module and mapped to the pathways are MMP2, VEGFA and CASP8, while for the cancers are BCL2, MDM2 and VEGFA." (PMID 28340554, 2017). "Specifically, MMP2 expression is upregulated when cancer cells are co-cultured with fibroblasts and mesothelial cells." (PMID 29221185, 2017). "The hYSK1-mediated inactivation of p16INK4a results in elevated MMP-2 promoter activity, which contributes to increased migration of cancer cells under hypoxia." (PMID 29179500, 2017). "Matrix metalloproteinase-2 (MMP-2) is an extracellular matrix degrading enzyme which has been shown to play important roles in different cancers." (PMID 28234925, 2017). "Particularly elevated levels of MMP2 and MMP9 were found in various cancers as kidney and are associated to a poor prognosis." (PMID 29100286, 2017). "Growth of both cancer cell lines expressing MMP-2 and MMP-9 was stopped, and the cell number was reduced at 24 h and remained low during an observation period of 96 h." (PMID 27295081, 2016). "It was reported that hypoxia-activated HIF-1α reduced E-cadherin expression and augmented MMP-2 expression during cancer cell migration." (PMID 26880989, 2016). "Matrix metalloproteinases are important contributors to the invasive and metastatic properties of cancer cells, their expression (especially MMP-2 and MMP-9) being elevated in a range of carcinomas." (PMID 28933410, 2016).
cancer (continued). "We conclude that the novel small-molecule inhibitor AC-73 inhibits HCC mobility and invasion, probably by disrupting CD147 dimerization and thereby mainly suppressing the CD147/ERK1/2/STAT3/MMP-2 pathways, which are crucial for cancer progression." (PMID 26882566, 2016). "MMP-2 and–9 play an important role in cancer cell migration and invasion by cleaving proteins of the extracellular matrix." (PMID 27282478, 2016). "This is consistent with the previous reports that NF-κB is the upstream of MMP-2 in various cancer cells." (PMID 26942004, 2016). "MMP2 was highly express in cancer cells to enable cells to break down surrounding tissue for the invasive behavior." (PMID 27791203, 2016). "Previous studies showed that FOXM1 promotes cancer cell migration and invasion by increasing the activities of MMP2 and MMP9." (PMID 27034162, 2016). "Malignant cells produce proteolytic enzymes, including serine proteinase, cathepsins, metalloproteinases (MMPs), and heparanase, among which MMP-9 and MMP-2 play key roles in destroying the basement membrane for mediating cancer invasion and metastasis." (PMID 27391337, 2016). "The results indicated that B7-H3 had a close relationship with MMP9 and MMP2 expression in cancer cells." (PMID 27145365, 2016). "The synergistic combination of metformin and MEK-Is strongly inhibited the binding of NF-κB to the MMP9 and MMP2 promoters, thereby suppressing their expression and the metastatic potential of cancer cells." (PMID 26673006, 2016). "This is consistent with previous reports that various medications can inhibit the cell migration and invasion of various cancer cells through the inhibition of MMP-2." (PMID 26942004, 2016). "Recently, it was reported that an LM5 fragment binds to the epidermal growth factor receptor and stimulates MMP-2 expression and cell migration as a possible mechanism leading to cancer invasion into the stroma." (PMID 27404587, 2016). "TIMP2, besides its activity in regulating MMPs, including MMP2, has a role in negatively regulating cellular response to growth factors, thus arresting cancer sprouting." (PMID 27288264, 2016). "MMP-2 plays an important role in creating a suitable microenvironment for the proliferation of cancer cells and contributes to epithelial–mesenchymal transition (EMT)." (PMID 27271600, 2016). "Our data also showed that accompanied with the increasing of VE- cadherin, CD133+ cancer stem-like cells had the higher level of MMP-2 and MMP-9." (PMID 27074560, 2016). "It has been documented that NF-κB is critically important for MMP-9 to mediate cancer cell invasion, and the binding of CREB to promoter is centrally involved in MMP-2 gene expression and related to the malignancy of cancer cells." (PMID 27144433, 2016). "Generation of activated forms of MMP2 and MMP9 was associated with cancer cell migration and invasion in vitro and in vivo." (PMID 27034162, 2016). "It is well known that MT1-MMP plays a positively important role for cell growth in type I collagen gels and for cancer cell migration via activating proMMP2 into active MMP2." (PMID 27240342, 2016). "One of the limitations is - such type of ionizing radiation can enhance the metastatic nature in various kinds of cancer cells by increasing the expression as well as activities of MMP-2 and MMP-9 leading to great difficulties in radiotherapy." (PMID 27659937, 2016). "MMP-2 expression in cancer cells was correlated with female gender, stronger inflammation, and histopathological type of cancer (R = 0.460, p = 0.013; R = 0.690, p = 0.0001; R = −0.440, p = 0.005, resp)." (PMID 27429508, 2016). "We therefore used the dtACPPD system that was designed to recognize MMP2 in cancer cells, by means of it to target cancer cells." (PMID 27791203, 2016). "MMP-2, also known as gelatinase A, facilitates cancer cell invasion and metastasis by degrading collagen IV, V and X which are present in the ECM and basement membrane." (PMID 27695098, 2016).
cancer (continued). "The result showed that CD133+ cancer stem-like cells significantly exhibited the increased protein and mRNA levels of VE- cadherin, MMP-2 and MMP-9 (P < 0.05), compared with CD133− cells." (PMID 27074560, 2016). "The proteolytic activity of MMPs involves the ECM degradation and evidences have shown that the expression of specific MMPs, such as MMP-2 (Gelatinase A) and MMP-9 (Gelatinase B), are associated with a wide range of human cancers." (PMID 27834913, 2016). "Aberrant FOXM1 expression enhances the migration and invasion of cancer cells by upregulating the transcription levels of MMP2 and MMP9." (PMID 27034162, 2016). "MMP-2 is reported to induce VEGF expression through integrin αVβ3-mediated signaling pathway in cancer cells." (PMID 27695098, 2016). "Taken together, our data indicate thatquercetin is an effective anti-cancer agent against MMP-2- and MMP-9-mediatedmetastasis in EGFR-overexpressing HNSCC." (PMID 27510965, 2016). "MMP-2 and MMP-9 are implicated in photoaging and development of cancer and this study showed that 2% and 3% GTE inhibited expression of MMP-2 and MMP-9 post-UVR." (PMID 27618035, 2016). "Even if poorly inducible, MMP-2 has been found overexpressed in several tumors playing a role in both tumorigenesis and cancer progression." (PMID 27782083, 2016). "Seven cancer cell lines were analyzed for MMP-2 and MMP-14 expression levels by Western blotting analysis." (PMID 26314845, 2015). "Growing evidence suggests that MMP-2 and MMP-9 are deeply implicated in CVDs and cancers through vascular remodeling and the formation of new blood vessels (angiogenesis and arteriogenesis)." (PMID 26637202, 2015). "MMP-2 has a well-established role in regulating cancer cell invasion and metastasis, in a variety of cancer types, including CRC." (PMID 25605009, 2015). "To explore the underlying mechanisms of Nodal-elevated cancer cell motility, we detected the expression of key markers of the EMT process and MMP-2 in BxPC-3 and PANC-1 cells after treatment with rhNodal and SB431542." (PMID 25557170, 2015). "It has been demonstrated that MMP2 is closely correlated with VEGF signaling in cancer cell growth, invasion and metastasis." (PMID 25954957, 2015). "Previous reports have indicated that the mean serum level of MMP2 in cancer patients was significantly higher than in the control groups." (PMID 26540114, 2015). "Matrix metalloproteinases (MMPs) are highly involved in degradation of extracellular matrix, a key process of cancer metastasis, MMP2 and MMP9 are the principal enzyme involved and reported to be overexpressed in OSCC." (PMID 26540630, 2015). "Matrix metalloproteinases MMP-2/9, as essential factors to cancer invasion and metastasis, mainly rely on PI3K/AKT/mTOR in A549 and other carcinoma cells." (PMID 26061184, 2015). "In vitro study, MMP-14 is known as an important activator of pro-MMP-2 at the cell surface via the involvement of TIMP2; for this reason, the interactions among MMP-14, TIMP2 and MMP-2 are of importance in cancer cell invasion and migration." (PMID 26314845, 2015). "Accumulating evidence demonstrate that several MMPs (including MMP-2) expression and activation were regulated by p65 subunit up-regulation and nuclear translocation induced NF-κB activation in many human cancers." (PMID 26033551, 2015). "MiRNAs have been reported as an important regulator in cancer progression and metastasis, and our results indicate that resistin promotes cell migration by up-regulation of MMP-2 expression." (PMID 25404641, 2015). "Since the degradation of the basement membrane by MMP-2 is likely a necessary step for cancer invasion." (PMID 26113801, 2015). "It has been reported that MMP-2 and MMP-9 are overexpressed and implicated in promoting cancer cell invasion and metastasis in many cancers." (PMID 25402510, 2015).
cancer (continued). "The degradation of the extracellular matrix (ECM) and basement membrane are crucial steps in cancer invasion and metastasis and the proteolytic enzymes MMP-2 and MMP-9 are involved in this process." (PMID 26512779, 2015). "MMP-2 and MMP-9 can degrade the majority of ECM components and are profoundly associated with the process of cancer invasion and metastasis." (PMID 25633440, 2015). "The relationship between CD147 and MMP-9, MMP-2 and their relevance with patients’ prognosis and clinicopathological parameters have been studied in a variety of cancers." (PMID 26507719, 2015). "The levels of MMP2 in the SKOV3 and PC3 cancer lesions were estimated by IHC staining, which showed high expression of MMP2 (+++ and ++, respectively)." (PMID 26540114, 2015). "Overexpression of Matrix metalloproteinases (MMP-2/9) were believed to represent a strong invasion capability by degrading extracellular matrix (ECM) in cancer cells." (PMID 26522444, 2015). "Several studies reported that Aurora-A enhances cancer cell metastasis through MMP-2 expression in human cancers." (PMID 25889801, 2015). "It has been shown in breast, prostate and other cancers that soy isoflavones can inhibit cell detachment, invasion and the expression of proteases such as MMP-2 and MMP-9." (PMID 25655427, 2015). "MMP-2 degrades the extracellular matrix, which promotes cancer cell invasion, and we previousl found that CXCR4 promoted human cancer cell invasion by upregulating MMP-2." (PMID 26213494, 2015). "miR-29 family plays a dominant role in regulating extracellular matrix genes, such as collagens, LAMA2, integrin β, Mmp2, fibrillin, secreted protein, acidic, and Sparc, consequently contributing to the promotion of cancer cell migration and metastasis." (PMID 25889078, 2015). "Related to the pro-cytolytic melittin, by taking advantage of tumor matrix metalloproteinase 2 (MMP2) overexpressed on cancer cell membranes, an MMP2 cleavable melittin/avidin conjugate was built." (PMID 25835385, 2015). "We then examined the influence of EGF on MMP9 transcription as well as on the transcription of additional MMPs (MMP-1, MMP-2, MMP-3, MMP-7, MMP-10, MMP-13, MMP14, MMP15) and of CD44, a cell adhesion glycoprotein implicated in EMT and cancer metastasis." (PMID 26084289, 2015). "Among the MMPs, MMP-2 and MMP-9 have been implicated in human cancer invasion, and we investigated the relationship between these two genes and miR-221/222 in this study." (PMID 25883224, 2015). "In conclusion, scutellarein effectively suppressed the invasion and migration of HT1080 cells by inhibiting the expression and activity of MMP-2, -9 and -14, which are crucial enzymes in cancer metastasis." (PMID 25394920, 2015). "Invasion processes require upregulation of proteolytic enzymes, such as MMP-2/9, to degrade extracellular matrix, thereby facilitating the invasion of cancer cells to surrounding tissues." (PMID 26501276, 2015). "The overexpression of PP4C promoted cancer cell growth and invasion and markedly increased the MMP-2/MMP-9 activities through a PI3K/AKT-dependent signaling pathway." (PMID 25927939, 2015). "Previous studies indicated that the transcription factor, CREB, plays an important role in controlling MMP-2 expression in various cancer cell lines." (PMID 25605016, 2015). "Many studies have shown that MMP-2 is overexpressed in tissues of various human cancer, including BC." (PMID 25816052, 2015). "Reverse zymography is a modification of traditional zymography by incorporating gelatin into the gel matrix as well as conditioned media from cancer cells as a source of MMP-2 and -9 activity." (PMID 24616631, 2014). "Increased expression of MMP-2 is a sign of poor prognosis in cancer of the stomach and pancreas as well as the prostate." (PMID 25097794, 2014).